ZNF605 (zinc finger protein 605)
Description:
May be involved in transcriptional regulation.
Tractability: PROTAC: UniProt records ubiquitination sites on it; ubiquitination databases record sites on it.
Gene: Protein-coding gene on chromosome 12 (132,918,306 to 132,956,306, reverse strand). Ensembl gene ENSG00000196458.
Subcellular location: Nucleus
Subcellular location (Human Protein Atlas): Nucleoplasm; Vesicles
Pathways (Reactome):
Gene expression (Transcription): Generic Transcription Pathway
Gene Ontology:
Biological process: regulation of DNA-templated transcription
Cellular component: nuclear lumen; nucleus
Genetic constraint (gnomAD): Loss-of-function variants: 9 observed, 8.25 expected, observed/expected ratio (o/e) 1.09, 90% interval 0.65 to 1.77. That is too few expected variants to judge how well the gene tolerates losing a copy. Missense variants: 673 observed, 798.91 expected, observed/expected ratio (o/e) 0.84, 90% interval 0.79 to 0.9. Synonymous variants: 255 observed, 272.31 expected, observed/expected ratio (o/e) 0.94, 90% interval 0.85 to 1.04.
Homologues: Orthologues: chimpanzee ZNF605 (98% identical), macaque ZNF605 (96% identical), dog ZNF605 (88% identical), pig ZNF605 (87% identical), rabbit ZNF605 (79% identical), rat Zfp605 (68% identical), mouse Zfp605 (65% identical). Paralogues in human: ZNF182 (50% identical), ZNF33B (50% identical), ZNF484 (50% identical), ZNF41 (49% identical), ZNF658 (49% identical), ZNF717 (47% identical), ZNF585B (47% identical), ZNF175 (46% identical), ZNF197 (46% identical), ZNF630 (45% identical), ZNF28 (45% identical), ZNF300 (44% identical), and 164 more.
Diseases named in the same sentence as ZNF605 in open-access papers:
ZNF605 is named in the same sentence as 4 diseases in open-access papers, as found by Europe PMC text mining. Sharing a sentence is not in itself a finding about the gene and the disease. The quoted sentences say what the papers report.
breast carcinoma (1 paper, 2025). "Cathepsin F can mediate the effects of ANXA2R and ZNF605 on in situ breast cancer." (PMID 39944834, 2025).
liver cancer (1 paper, 2023). An epithelial or non-epithelial malignant neoplasm that arises from the liver. "ZFP57 and ZNF605 demonstrate binding to a significant number of LTR12C elements present in liver cancer PMDs, suggesting that binding of these KZFPs could maintain the methylation at LTR12Cs." (PMID 37470704, 2023).
ZNF605 also shares sentences with these, for which no sentence is quoted: cervical cancer (1 paper); infection (1).